MPO (myeloperoxidase)
Diseases named in the same sentence as MPO in open-access papers (continued):
Sharing a sentence is not in itself a finding about the gene and the disease.
Sepsis (continued). "Additionally, MPO-DNA and cf-DNA levels were significantly higher in non-sepsis patients than in healthy controls, indicating that abnormal NET formation may also occur in general inflammatory diseases." (PMID 39457503, 2024). "Thus, the authors show that finding that wild-type and MPO knockout mice are similarly and significantly susceptible to alcohol-induced mortality in sepsis indicates that alcohol does not act primarily by inhibiting expression or function of MPO." (PMID 31739600, 2019). "Finally, the expression of the topmost upregulated genes (ARG1, IL1R2, ELANE, MMP9) was quantified by reverse transcriptase-PCR (RT-PCR), and myeloperoxidase (MPO) expression was confirmed by immunohistochemistry (IHC) staining in the lungs of a well-established sepsis mouse model." (PMID 31817302, 2019). "Myeloperoxidase could eventually help in diagnosing sepsis and predicting mortality." (PMID 28916973, 2017). "Thus, in addition to SOD, MPO may be considered a modulator of NO• signaling during inflammation, and this may be relevant in sepsis where the inflammation response may contribute substantial MPO." (PMID 28686196, 2017). "MPO could also differentiate between patients with sepsis and patients with septic shock." (PMID 28916973, 2017). "Several studies have investigated the role of MPO in monitoring cardiovascular disease primarily related to the inflammation observed in atherosclerosis, while the DNA oxidative product, 8-OHdG, is reported to be a relevant marker of sepsis-related oxidative stress and outcome." (PMID 24691127, 2014). "To further assess the diagnostic potential of these biomarkers, we examined the ability of MPO and CIT-HIST-H3 to identify sepsis-related DIC in our patient group." (PMID 41476244, 2025). "NETs-MPO-anchored ENO1 mediates the role of NETs-DNA in promoting Treg differentiation and function in sepsis-induced immunosuppression via a newly identified DNA sensor IFITM2." (PMID 40892462, 2025). "MPO, a key enzyme in NET formation, has also been identified in several studies as a marker of neutrophil activation and the disease severity in both sepsis and COVID-19." (PMID 40806591, 2025). "Our research focused on measuring MPO and CIT-HIST-H3 levels across various participant groups, yielding insights into their roles in sepsis development." (PMID 41476244, 2025). "LPS-induced sepsis changed the gastric mucosal barrier by reducing its phospholipid content, PGI2, and somatostatin levels, as well as increasing MPO, TXB2, LTB4, PLA2, and MDA." (PMID 39765810, 2024). "To address this issue, we conducted a retrospective study to analyze the predictive role of MPO and HOCl for NOAF in sepsis." (PMID 39030470, 2024). "Based on their high differential methylation levels and their role in the immune functions identified, four genes (SERPINA1, AZU1, MPO and SLX4) were selected for further validation, supported by available evidence of their biological roles in sepsis." (PMID 39926115, 2024). "SERPINA1, AZU1, MPO and SLX4 genes stand out for their correlation with inflammation and severity and have potential as biomarkers for diagnosing sepsis and predicting poor prognosis." (PMID 39926115, 2024). "The combination of MPO and its derivative HOCl with clinical indicators improves the prediction of NOAF in sepsis." (PMID 39030470, 2024). "In this study, MPO-DNA complexes and cf-DNA were selected as marker molecules of NETs to explore the changes in NET levels in sepsis patients." (PMID 39457503, 2024). "In our study, an increase in bacterial load was identified 24 h after sepsis induction with an increase in neutrophil infiltration and edema in hepatocytes in the CLP+SAL group, as observed through increased liver mass and MPO levels." (PMID 39199173, 2024).
Sepsis (continued). "The results showed that SOFA scores were significantly higher in both the high MPO-DNA and high cf-DNA groups compared to the low-level groups, suggesting that NET levels are significantly elevated in severe sepsis patients." (PMID 39457503, 2024). "Overall, these findings underscore the potential of DNA methylation as biomarkers in sepsis, particularly for AZU1, MPO, SERPINA1, and SLX4, which show strong correlations with clinical indicators of severity and inflammation." (PMID 39926115, 2024). "In this study, ISE pretreatment significantly decreased MPO plasma levels, a marker of NET burden induced by CLP-induced sepsis." (PMID 38921594, 2024). "PAG-treated WT and Cth−/− mice following CLP had significantly less MPO activity in both the liver and lung than mice with WT CLP-induced sepsis." (PMID 37686458, 2023). "A major feature of sepsis is the activation of leukocytes that will release proteases, cytotoxic enzymes, ROS and reactive nitrogen species (RNS) and the myeloperoxidase-derived oxidant (MPO) hypochlorous acid contributing to the killing of bacteria (HOCl)." (PMID 36980160, 2023). "To investigate the involvement of NETs in SI-ALI and coagulation cascades, we measured the levels of dsDNA and MPO-DNA, the well-established indicators of NET formation, in patients with sepsis and matched healthy controls." (PMID 37626060, 2023). "In particular, the upregulation of MPO, MMP9, TLR2, and LCN2 in the lungs of sepsis-induced ARDS mice suggests their crucial role in developing lung injury in COVID-19 and sepsis." (PMID 37822934, 2023). "Increased MDA and MPO levels and decreased SOD and CAT activities demonstrate sepsis-induced ovarian tissue damage in the present study." (PMID 36648023, 2023). "There was increased MPO activity in both the liver and lungs of mice with WT CLP-induced sepsis compared to sham control mice." (PMID 37686458, 2023). "Our results showed that genes such as IFN-γ, TNF-α, IL-6, MIP-2, IL-10, KC (CXCL1), CCL-2, MPO, MMP9, TLR2, and LCN2 were significantly upregulated in the lungs of sepsis-induced ARDS mice compared to control mice." (PMID 37822934, 2023). "Oxidative stress leads to excessive production of MPO and MDA, and reduces the expression of antioxidant enzymes such as SOD and GSH, resulting in lung damage in experimental sepsis in rats [PMID: 21,782,879]." (PMID 35266443, 2022). "It is worth noting that many of these proteins, such as MPO and CD28, have been reported to play a role in sepsis." (PMID 35739592, 2022). "In a rat model of sepsis, it was found that the use of resveratrol can reduce the levels of MDA and myeloperoxidase in lung and kidney tissues and increase the content of glutathione." (PMID 35222035, 2022). "Among the genes identified through the PPI network, many genes such as MPO, CD28, and TLR8 have been reported to play a vital role in sepsis." (PMID 35739592, 2022). "Next, we measured the level and fold change of sepsis biomarkers such as DNI, MPO, PCT, and TNF-α at baseline, 6 h, 24 h and 48 h post-CLP." (PMID 35334545, 2022). "To address this, we comparatively measured the level and cost-effectiveness of sepsis biomarkers such as DNI, MPO, PCT, and, TNF-α in a CLP-induced sepsis mouse model mimicking human sepsis." (PMID 35334545, 2022). "The animals with sepsis revealed a significant rise in MDA levels, MPO activity, and amount of collagen in lung and kidney tissues along with a decrease in glutathione levels." (PMID 36588685, 2022). "Third, the cost-effectiveness between sepsis biomarkers indicated that the rank of clinically applicable biomarkers is DNI, PCT, TNF-α, and MPO in descending order." (PMID 35334545, 2022). "In a previous study, [18F]FDG PET lung uptake was found to precede increased CT attenuation (lung edema) in a model of sepsis and ARDS, which was accompanied by neutrophil influx reflected by increased myeloperoxidase activity." (PMID 36439175, 2022).
Sepsis (continued). "Collectively, these data indicate that DNI in CLP-induced sepsis mice is as effective as the existent inflammatory biomarkers such as MPO, PCT and TNF-α to predict the prognosis of sepsis." (PMID 35334545, 2022). "ELANE, MPO and CD177 were among the highest expressed genes in transcriptome meta-analyses of sepsis whole blood transcriptomes." (PMID 34552111, 2021). "As pediatric sepsis severity increases, the levels of MMP9 and MPO decreased significantly (P < 0.05)." (PMID 33748037, 2021). "Our data identified that AE prominently increased MDA and MPO expression and prominently decreased SOD and GSH expression during sepsis." (PMID 34493741, 2021). "In the myocardial injury of sepsis model, EA at ST36 lowered CK-MB content in plasma and TNF-α, NO, and MPO contents in cardiac tissues." (PMID 35095910, 2021). "Among 167 sepsis patients, there was a strong positive correlation between HBP and MPO (r = 0.737, P < 0.001) as well as between IL-6 and IL-8 (r = 0.811, P < 0.001) on admission." (PMID 33461369, 2021). "ELANE, MPO, CD177, OLFM4 and OLAH gene expression were found to be comparable in both the groups sepsis and sterile inflammation indicating that neutrophil response to both bacterial infection and tissue injury involved upregulation of these genes." (PMID 34552111, 2021). "HII was also shown to be positively correlated with MPO and MCP-1, both of which are measures of oxidation and inflammation, and likely reflects increased oxidized lipids in sepsis." (PMID 34535154, 2021). "The induction of miR-199a in AMs during sepsis increases the release of pro-inflammatory cytokines (IL-1β, IL-6, and TNF-α), the MPO activity, ALI, and the high levels of CASP3, Bax and lowers the Bcl-2 levels." (PMID 32849610, 2020). "In the sepsis rat model, HBO treatment alleviated intestinal barrier dysfunction of rats by altering the activation of NF-κB, nitric oxide, and myeloperoxidase." (PMID 33178107, 2020). ") and MPO levels in BALF and lung homogenate of mice subjected to K. pneumoniae B5055-induced sepsis has been reported on all days in an experimental study." (PMID 32849610, 2020). "This study demonstrates the role of significant and widespread immune activation (IL1R2, MMP9), along with oxidative stress (ARG1) and the recruitment of neutrophils, in sepsis (ELANE, MPO)." (PMID 31817302, 2019). "In the muscular layer of the small intestine, blocking IL-17A ameliorated sepsis-induced inflammation, as evidenced by a decreased number of CD68+ macrophages and decreased levels of MPO activity." (PMID 31531179, 2019). "A 2018 study of 55 critically ill patients demonstrated rapid and sustained increases in the circulating levels of MPO-DNA complex in the serum, indicating NET formation in the early stages of sepsis." (PMID 31736963, 2019). "In severe bacterial infections, such as sepsis, a natural stimulation of production of endogenous granulocyte colony-stimulating factor is able to reduce MPXI values, releasing large amounts of MPO for bactericidal activities from activated neutrophils." (PMID 31640199, 2019). "This set of data and our previous study underscored the powerful potential of using the real-time PCR method to determine the involvement of genes such as MPO, CD177, and NF-κB in infectious diseases like sepsis." (PMID 31428666, 2019). "EA at Zusanli had a positive role in myocardial injury of sepsis rats by reducing the high TNF-α, MPO, and NO content, lowering plasma activity of CK-MB and moisture content." (PMID 30402132, 2018). "In this study, circulating levels of soluble NET remnants (MPO-DNA and cf-DNA) were investigated in patients with septic shock to evaluate the extent of NET formation during sepsis." (PMID 30005596, 2018). "The level of MPO, determined by the MPO staining, was significantly lower in the KO-CLP sepsis group than in the WT-CLP sepsis group in the liver and lung at 24 h after the CLP." (PMID 28694565, 2017).
Sepsis (continued). "In conclusion, we show that plasma levels of MPO correlate with severity of disease in SIRS patients in the ICU and discriminate between sterile inflammation and sepsis." (PMID 28916973, 2017). "In this study, we found that following sepsis there was an increase in the liver and lung CSE expression and H2S synthesizing activity which were correlated with augmented MPO activity as well as histological changes in the liver and lung." (PMID 27518439, 2016). "In the kidneys of knockout mice with sepsis, especially the MyD88 knockout mice, we found decreased expression of IL17, KC, iNOS, and MPO activity." (PMID 22655058, 2012). "Whatever triggered development of sepsis, the ensuing result is development of SIRS, together with tissue buildup of reactive oxygen species [ROS; including superoxide anion, H2O2, and myeloperoxidase products of H2O2, and the hydroxyl radical (HO." (PMID 23208733, 2012). "Cardiomyocyte p110α expression resulted in a normalization of MPO levels in the heart of CLP mice, indicating that transgene expression prevented neutrophil sequestration in the heart during sepsis." (PMID 23028587, 2012). "Both polymicrobial sepsis and intratracheally lipopolysaccharide (LPS) injection can induce acute lung inflammation with elevated IL-1β, KC, MIP-2 levels and MPO activity of lung in mice." (PMID 21906393, 2011). "Lung myeloperoxidase (MPO) activity, chemokine, and cytokine levels were measured to evaluate the beneficial effects, if any, of NK-2R antagonism in sepsis." (PMID 21188216, 2010). "In this study, for the first time in the specific context of SIC, we demonstrate that sepsis patients with SIC show significantly elevated plasma levels of GSDMD - NETs signature proteins (N - GSDMD and MPO - DNA), and these elevations independently correlate with the risk of SIC." (PMID 40766307, 2025). "Additionally, the association between CIT-HIST-H3 and the elevated JAAM2 score—used to diagnose DIC—was notably stronger than that with MPO, emphasizing the critical role of HIST-H3 in sepsis." (PMID 41476244, 2025). "Their levels were indicative for sepsis-related AKI, while MPO levels could also reflect myocardial and liver injury." (PMID 40731775, 2025). "Within 24 h of sepsis, bone marrow lactate accumulation reduces histone deacetylase HDAC3 activity, tripling H3K27ac enrichment at the promoters of myeloid genes critical for granulopoiesis [e.g., myeloperoxidase (MPO) and elastase (ELANE)]." (PMID 41446870, 2025). "Next, the ROC curves show that the ITGAM, CXCR2, and FCGR3B expression levels provide high accuracy for classifying the Sepsis and Control group (AUC > 0.9); MMP9, MPO, and CTSG expression levels exhibit moderate accuracy for this classification (0.7 < AUC < 0.9)." (PMID 41259376, 2025). "Overall, our findings suggest that MPO has considerable potential as a prognostic marker for short-term mortality and correlates with markers of end-organ damage in sepsis, independent of DIC status." (PMID 41476244, 2025). "The relative amount of different cell types including MPO-positive and NE-positive cells does not differ before and after sepsis." (PMID 39904820, 2025). "During sepsis, the bone marrow releases a large amount of immature granulocyte (IGs) through emergency granulopoiesis, such as CEACAM8+Neu, S100A8/9hiNeu, IL1R2+Neu, PADI4+Neu, MPO+Neu and cycling MK167+CYP1B1+Neu." (PMID 40356926, 2025). "Moreover, MPO, a key NET formation marker, was stepwise increased among healthy volunteers, septic patients and patients with sepsis-induced ARDS." (PMID 40731775, 2025). "Importantly, we established cutoff values for MPO (> 3.7 ng/ml) and CIT-HIST-H3 (> 3.6 ng/ml) that effectively differentiate between the activation of NETs formation in sepsis patients and healthy individuals." (PMID 41476244, 2025).
Sepsis (continued). "To explore the relationship between NET levels, the severity of sepsis, and PCT levels in sepsis patients, we divided the sepsis patients into high- and low-concentration groups based on the average levels of the NET marker MPO-DNA and the median cf-DNA levels." (PMID 39457503, 2024). "The activity of myeloperoxidase and the concentration of ICAM1 and VCAM1 in the liver and lungs, as well as the expression of ICAM1 and VCAM1 on vascular endothelial cells in these tissues, increased in mice with CLP surgery-induced sepsis." (PMID 38928206, 2024). "One study showed increased MPO in obese mice at 1-, 6-, and 18-h post-sepsis compared to non-obese mice." (PMID 38388878, 2024). "Blood plasma levels of the azurophilic granule enzyme myeloperoxidase were previously shown to be elevated in sepsis and especially septic shock compared to SIRS suggesting a higher degree of granulocyte degranulation in sepsis than SIRS." (PMID 39434093, 2024). "To investigate whether NET formation changes in sepsis patients, we measured the levels of the NET markers MPO-DNA and cf-DNA in the three groups." (PMID 39457503, 2024). "Subsequently, based on an external validation cohort from our hospital, qRT-PCR demonstrated significant up-regulation on LTF, LCN2, ELANE, MPO, and CEACAM8 in peripheral blood of sepsis patients versus controls, thus further enhancing the reliability of the findings." (PMID 38912048, 2024). "In addition, the expression levels of LTF, LCN, ELANE, MPO, and CEACAM8 were all up-regulated in the peripheral blood of sepsis patients than critical controls in the GSE131761 dataset, which is consistent with the previous findings." (PMID 38912048, 2024). "Levels of myeloperoxidase protein (MPO), a heme-containing peroxidase expressed mainly by neutrophils to participate in pathogen clearance, were also increased at 4 and 7 h after CLP-induced sepsis initiation, and decreased thereafter." (PMID 39200137, 2024). "Another noted MPO elevation at 12 and 24 h in obese septic mice compared to obese non-septic mice, and a third observed MPO increase at 18 h in obese mice compared to non-obese mice post-sepsis and obese non-septic mice." (PMID 38388878, 2024). "Two (67%) saw higher liver MPO levels in obese septic mice at 6-h post-sepsis compared to non-obese septic mice, and one showed an increase at 18 h." (PMID 38388878, 2024). "Additionally, pretreatment with GdCl3 in CLP-induced sepsis significantly increased the expression of various cytokines, including TNF-α, and increased the MPO activity and infiltration of leukocytes in the lung tissue." (PMID 38254684, 2024). "Sepsis increased the pulmonary vascular permeability, as determined by the Evans blue assay, resulted in more ROS and MDA production, promoted caspase-3 activity, and increased MPO activity in lung tissues." (PMID 38057866, 2023). "However, sepsis cases with increased levels of mRNA of DHCR7, GABARAPL2, MAOA, MPO, PDZD8, and TFRC had worse overall survival." (PMID 38011291, 2023). "Similarly, we also discovered that, in addition to great up-regulation in the plasma of sepsis patients and sepsis rats (CLP group), the NET formation markers (histone H3 and MPO) levels were positively correlated with the number of PEVs in sepsis patients." (PMID 37559007, 2023). "Finally, we found a significant correlation between eryptosis and other biomarkers of sepsis such as EAA, IL-6 and MPO." (PMID 37762478, 2023). "In a recent observational study, MPO levels measured in critically ill patients at the time of ICU hospitalization allowed us to distinguish septic patients from patients without sepsis." (PMID 37762478, 2023). "By immunohistochemistry and immunofluorescence methods, we found that myeloperoxidase expression significantly increased in sepsis on day 1, higher levels of CCL5 occurred at the plasma level as early as 12 h post-sepsis, and CCL5 mRNA levels increased in parallel with those in the muscularis." (PMID 37063880, 2023).